SNORD24 (small nucleolar RNA, C/D box 24)
Synonyms: U24; RNU24
Gene: Small nucleolar RNA gene on chromosome 9 (133,349,396 to 133,349,470, forward strand). Ensembl gene ENSG00000206611.
Gene Ontology:
Biological process: RNA processing
Cellular component: nucleolus
Homologues: Orthologues: chimpanzee SNORD24 (100% identical), macaque SNORD24 (97% identical), pig SNORD24 (93% identical), rat Snord24 (93% identical), guinea pig SNORD24 (92% identical), dog SNORD24 (89% identical), dog SNORD24 (88% identical), mouse Gm23969 (85% identical), zebrafish SNORD24 (83% identical), tropical clawed frog SNORD24 (80% identical), rabbit SNORD24 (77% identical), tropical clawed frog SNORD24 (77% identical).
Diseases named in the same sentence as SNORD24 in open-access papers:
SNORD24 is named in the same sentence as 2 diseases in open-access papers, as found by Europe PMC text mining. Sharing a sentence is not in itself a finding about the gene and the disease. The quoted sentences say what the papers report.
colon cancer (1 paper, 2017). "Moreover, SNORD24 was significantly overexpressed in HT-29 (1.4-fold, p < 0.05) and HCT-116 (6.1-fold, p < 0.01) colon cancer cell lines in comparison with the CCD-18Co normal colon cell line." (PMID 28051134, 2017).
SNORD24 also shares sentences with these, for which no sentence is quoted: multiple sclerosis (2 papers).